SMAD3 (SMAD family member 3)
Diseases named in the same sentence as SMAD3 in open-access papers (continued):
Sharing a sentence is not in itself a finding about the gene and the disease.
cervical carcinoma (22 papers, 2015 to 2024). A carcinoma arising from either the exocervical squamous epithelium or the endocervical glandular epithelium. "Different studies found an increased expression of miR‐142‐5p in cervical cancers in comparison to normal cervical tissues that favored cervical cancer progression by targeting Wnt/β‐catenin pathway and SMAD3, a negative regulator of TGF‐β signaling." (PMID 37899663, 2024). "The expression of TGF-β1, TβRI, p-Smad2 and p-Smad3 were analyzed in a total of 30 cervical cancer and normal tissue samples." (PMID 35975844, 2023). "Smad3 interacts with PKCε and this interaction promotes cervical cancer angiogenesis; therefore, Smad3 was selected for protein-protein docking." (PMID 37667176, 2023). "The expression of TGF-β1, TβRI, p-Smad2 and p-Smad3 was significantly enhanced in cervical cancer samples and cervical cancer cell lines." (PMID 35975844, 2023). "As demonstrated in Fig. (3A-D), the expression of TGF-β1, TβRI, p-Smad2 and p-Smad3 was significantly enhanced in cervical cancer samples (p<0.05)." (PMID 35975844, 2023). "The levels of transforming growth factor-β1 (TGF-β1), transforming growth factor-β type I receptor (TβRI), phosphorylated (p-) Smad2 and p-Smad3 in cervical cancer samples were measured." (PMID 35975844, 2023). "Recently, it was reported that ACTA2-AS1 is significantly over-expressed in cervical cancer, upregulating SMAD3 expression by competitively sponging miR-143-3p." (PMID 33845844, 2021). "Zhou and colleagues reported that miR-195 suppressed cervical cancer migration and invasion through targeting Smad3." (PMID 28471382, 2017). "While OX40L, OX40 and Smad3 mRNA level profile in normal cervix was higher than that in cervical cancer." (PMID 28086903, 2017). "Smad3 is also known to mediate carcinogenic processes, particularly in cervical cancer." (PMID 37667176, 2023). "Similarly, OIP5-AS1 promoted viability, migration and invasion of cervical cancer cells via binding with miR-143-3p and upregulating SMAD3 expression in cervical cancer cells." (PMID 35756672, 2022). "Firstly, we verified the expression of SMAD3 in cervical cancer tissues and cell lines." (PMID 32774166, 2020). "As the mRNA level of OX40 and Smad3 was decreased in neoplastic foci and pericarcinous tissues, the potential congenerous effect of OX40 and Smad3 might be weakened in local microenvironment of cervical cancer." (PMID 28086903, 2017). "Thus, targeting SMAD3 and modifying the SMAD3-dependent tumor microenvironment may be an effective therapeutic approach against cervical cancer." (PMID 32774166, 2020). "The expression of PVT1 is upregulated in cervical cancer cells, and PVT1 binds directly to miR-140-5p, which promotes the expression of Smad3 and then promotes the development of cervical cancer." (PMID 35103065, 2022). "To analyse the relationship between these proteins and FAD104 in TGF-β–induced EMT of cervical cancer cells, we clarify the molecular mechanism by which FAD104 regulates the phosphorylation of Smad1/5/8 and Smad3 in the next paper." (PMID 29180690, 2017). "In addition, the protein levels of TGF-β1 and TβRI and the phosphorylation levels of Smad2/3 (p-Smad2 and p-Smad3) were significantly increased in HeLa and SiHa cells, indicating that the TGF-β1/Smad2/3 pathway was activated in cervical cancer." (PMID 35975844, 2023). "Since transforming growth factor- beta (TGF-β), SMAD3 and hypoxia inducible factor 1 alpha (HIF-1α) are upstream factors of DEC1, the DEC1 increases in cervical cancer cells may depend on their function under hypoxia and inflammation." (PMID 33089188, 2020). "In summary, these results showed that the level pattern of mRNA of FoxP3, CCL22/CCR4, OX40L/OX40 and Smad3 in cervical cancer immune microenvironment distinctly differed from that in normal cervix." (PMID 28086903, 2017).
cervical carcinoma (continued). "Another report reviewed that cell cycle progression was regulated by the SMAD2/SMAD3 pathway, which is consistent with the study that SMAD2 overexpression could promote cervical cancer cell growth by facilitating the G1/S phase transition." (PMID 26356815, 2015).
colitis (22 papers, 2013 to 2025). Inflammation of the colon. "We previously observed that RA synthesis inhibition via WIN 18,446 treatment decreased the expression of α4β7 in activated CD4+ T cells; this was associated with decreased colitis and increased survival in Smad3−/− mice." (PMID 37764666, 2023). "Smad2/Smad3 double deficient mice develop fatal inflammatory diseases with reduction in Foxp3 expression in CD4+ T cells while Smad2 deficiency make mice susceptible to DSS induced colitis." (PMID 28003811, 2016). "However, Smad3+/− mice did develop clinical signs of colitis, including bloody diarrhea and weight loss, but only a small number of animals developed severe disease requiring euthanasia." (PMID 24244446, 2013). "Signs of colitis also developed in Smad3+/− mice, however, on average, clinical signs such as weight loss and presence of bloody diarrhea were less severe compared to Smad3−/− mice." (PMID 24244446, 2013). "We previously reported that WIN 18,446 treatment increased survival and decreased colitis severity in Smad3−/− mice in which H. bilis induced a rapid-onset (<7 days post-infection) severe colitis." (PMID 37764666, 2023). "Our group has also used this inhibitor to study colitis, and showed that WIN 18,446 treatment reduced RA synthesis in vivo and suppressed colitis in an acute mouse model of IBD using Smad3−/− mice." (PMID 37764666, 2023). "Preventive and therapeutic administration of metformin to chronic TNBS or DSS colitis mice indicated that metformin significantly attenuated intestinal fibrosis by suppressing Smad3 phosphorylation." (PMID 35645830, 2022). "In conventionally housed IL-37tg mice with DSS induction, IL-37 receptors Il-18r1 and Il1rapl1 mRNA levels and additional downstream signaling pathway genes (Jun, Myd88, Sigirr, Smad3, Stat1, and Stat3) were expressed similarly as in control WT colitis mice." (PMID 35836813, 2022). "In both these models, the elevated levels of Smad7 associate with reduced Smad3 phosphorylation, and colitic mice given oral Smad7 AS show enhanced phosphorylation of Smad3, reduced synthesis of inflammatory cytokines and amelioration of colitis." (PMID 33920230, 2021). "One study in Smad3-/- colitis-prone mice found that in dietary DHA enhanced LPS-induced B-cell secretion of IL-6 and TNFα, and also increased CD40 expression versus controls." (PMID 33603741, 2020). "A current study has indicated that downregulated lnc-Smad3 exerts a protective effect on colitis by recruiting Ash1l to the Smad3 promoter and regulating Tregs polarization." (PMID 30150986, 2018). "In a Smad3−/−/bacteria-driven model of murine colitis/CRC, vitamin D supplementation reduced colonic inflammation and decreased development of CRC." (PMID 27417758, 2015). "In the murine TNBS-model of colitis, vitamin D deficiency lead to worse disease activity and fibrosis as determined by collagen deposition, possibly through the TGF-β1/Smad3 pathway." (PMID 27417758, 2015). "Our studies demonstrate that SMAD3 is important in the repair phase of DSS-induced colitis, as most 3% DSS-exposed Smad3−/− mice succumbed to disease prior to 5 weeks post DSS treatment." (PMID 24244446, 2013). "For this reason, Smad3-/- mice, harboring a deletion for the Smad3 signaling molecule downstream of the TGF-β receptor, are often used in combination with pathobiont bacterial species such as Helicobacter bilis and H. hepaticus to study colitis-associated CRC." (PMID 32706816, 2020). "We determined if inhibition of RA synthesis by WIN 18,446 influences colitis in Smad3−/− mice." (PMID 32987910, 2020). "Both increased expressions of TGF-β1 and Smad3 have been demonstrated in TNBS colitis." (PMID 31275422, 2019). "In contrast, in the DSS-induced colitis model, GPR15 activation enhances SMAD3/STAT5 signaling and promotes the differentiation of iTregs, thereby contributing to intestinal integrity." (PMID 40957881, 2025).
colitis (continued). "In addition, the antifibrotic effects of glutamine in TNBS induced colitis was partly attributed to abrogation of the overexpression of TGF-β, phosphorylated Smad3, and TIMP-1." (PMID 25948887, 2015). "Indeed, upregulation of ALK5 and TIMP-1, phosphorylation of Smad2 and Smad3 proteins, and increased intestinal wall collagen deposition were found in anaerobic bacteria- and TNBS-induced colitis." (PMID 25948887, 2015). "This seemingly paradoxical increase in the anti-inflammatory TGF-β in DSS-induced colitis may be due to overexpression of SMAD7, which negatively regulated TGF-β signaling by competing for SMAD3’s binding site on the TGF-β receptor, thereby blocking SMAD3 activation." (PMID 33859564, 2021). "During chronic colitis, also the deregulation of Tgf-β signaling was partially restored compared to acutely DSS-treated mice as indicated by lack of Tgf-β upregulation and milder upregulation of Smad-3 in chronically DSS-treated compared to untreated mice." (PMID 36232813, 2022).
Loeys-Dietz syndrome (21 papers, 2015 to 2025). Loeys-Dietz syndrome is a rare genetic connective tissue disorder characterized by a broad spectrum of craniofacial, vascular and skeletal manifestations with four genetic subtypes described forming a clinical continuum. "LOF missense mutations in SMAD2 and SMAD3 causing Loeys-Dietz syndrome, another syndromic TAA form, are also located in the MH1 and MH2 domains." (PMID 28659821, 2017). "Mutations in SMAD3, have been identified in up to 2% of patients with familial thoracic aneurysms leading to acute aortic dissection Patients with the Loeys-Dietz syndrome have mutations in receptors for TGF-β (TGFBR1 and TGFBR2)." (PMID 26925344, 2016). "Among the genes queried, COL3A1 and aggregated testing of Loeys-Dietz syndrome-associated genes (TGFBR1, TGFBR2, SMAD2, SMAD3, TGFB2, TGFB3) were the leading signals of enrichment, consistent with prior studies [21•, 24, 25]." (PMID 37979122, 2023). "TGFBR1/2 and SMAD2/3 encode proteins involved in TGF-β signaling and mutations in these genes cause Loeys-Dietz syndrome (LDS) in patients (TGFBR1; LDS1; MIM 609192, TGFBR2; LDS2; MIM 61068, SMAD2; LDS6; MIM 619656, SMAD3; LDS3 (AOS); MIM 613795)." (PMID 35492343, 2022). "Patients with the Loeys-Dietz syndrome (LDS) have mutations in the TGF-βR1, TGF-βR2, and SMAD3 genes." (PMID 32273946, 2020). "A surgical series of Loeys-Dietz syndrome confirmed high rates of proximal aortic surgery, where 18% with TGFBR1, 48% with TGFBR2, and 27% with SMAD3 pathogenic variants underwent surgery." (PMID 31795342, 2019). "Within the Loeys-Dietz syndrome group, mean freedom from death was similar with TGFBR1 (70 ± 3 years, 95% CI 64–77), TGFBR2 (73 ± 5 years, 95% CI 63–83), and SMAD3 pathogenic variants (76 ± 6 years, 95% CI 64–89; p = 1.000)." (PMID 31795342, 2019). "Within the Loeys-Dietz syndrome group, mean freedom from proximal aortic surgery was similar with TGFBR1 (48 ± 5 years, 95% CI 38–58), TGFBR2 (49 ± 5 years, 95% CI 39–58), and SMAD3 pathogenic variants (68 ± 6 years, 95% CI 55–80; p = 0.143)." (PMID 31795342, 2019). "Therefore, we performed this observational case-matched comparison of a Loeys-Dietz syndrome group including 83 individuals with a pathogenic variant in the three most common genes identified in Loeys-Dietz syndrome (TGFBR1, TGFBR2, and SMAD3) gene." (PMID 31795342, 2019). "Among these, Loeys-Dietz syndrome (MIM # 609,192) shows mutations in other genes which are involved in the same pathway of FBN1 and include TGFBR1 (MIM * 190,181), TGFBR2 (MIM * 190,182), SMAD3 (MIM * 603,109), TGFB2 (MIM * 190,220), TGFB3 (MIM * 190,230) and SMAD2 (MIM * 601,366)." (PMID 39008115, 2024). "Among them, 51 patients had genetically confirmed HTAD (Marfan syndrome (FBN1), Loeys-Dietz syndrome (TGFBR1, TGFBR2, SMAD3, TGFB2), vascular Ehlers-Danlos syndrome (COLSA1), and non-syndromic HTAD (ACTA2, MYH11, MYLK))." (PMID 41310758, 2025). "Similarly, while TGFBR1- and TGFBR2-related Loeys-Dietz syndrome are included in the IUIS gene list for IEI, SMAD3-related Loeys-Dietz syndrome is not, despite manifesting with many of the same symptoms." (PMID 37215141, 2023).
triple-negative breast carcinoma (21 papers, 2014 to 2025). An invasive breast carcinoma which is negative for expression of estrogen receptor (ER), progesterone receptor (PR), and human epidermal growth factor receptor 2 (HER2). "It promotes m6A-modified SMAD3 nuclear export to augment the TGF-β signaling cascade leading to triple negative breast cancer metastasis." (PMID 40221424, 2025). "Silencing DARS-AS1 enhanced the sensitivity of triple-negative breast cancer (TNBC) cells to doxorubicin by suppressing autophagy induced by the TGF-β/Smad3 signaling pathway, thereby strengthening the synergistic antitumor effects." (PMID 38322590, 2024). "We examined associations of CCL2, CCR2, phospho-SMAD3 and phospho-p42/44MAPK with molecular subtype including: luminal A and B, HER2+ and triple negative breast cancers, which were identified using clinical guidelines on ER, PR, HER2 and Ki67/PCNA expression." (PMID 33888841, 2021). "In summary, we identified a marked decrease in Smad2 protein levels to increase the Smad3 to Smad2 protein ratio in several human triple negative breast cancer cell lines." (PMID 31798766, 2019). "Similarly, gradient rotating magnetic fields have been reported to impair F-actin-related gene CCDC150, thereby inhibiting triple-negative breast cancer metastasis by inactivating the TGF-β1/SMAD3 signaling pathway." (PMID 40552270, 2025). "Here we report that ZNF165, a CT antigen frequently expressed in triple-negative breast cancer (TNBC), associates with SMAD3 to modulate transcription of transforming growth factor β (TGFβ)-dependent genes and thereby promote growth and survival of human TNBC cells." (PMID 32515734, 2020). "Unlike in mice, where Smad2 deficiency is embryonic lethal and Smad3 deficient mice are viable and fertile, Smad3-deficiency in MDA-MB-231 triple negative breast cancer cells retarded their growth similar to TMEPAI knockdown and Smad2 deficient cells behaved like wildtype cells." (PMID 31798766, 2019). "Our studies are the first to report that cells may escape TGF-β mediated growth suppression in triple negative breast cancer by altering endogenous Smad2 and Smad3 protein levels." (PMID 31798766, 2019). "However, this ratio is increased in most triple negative breast cancer cells (Smad3/Smad2 > 1.0) except for MDA-MB-453 cell line (Smad3/Smad2 = 0.1)." (PMID 31798766, 2019). "Indeed, inhibition of CDK4 in a triple-negative breast cancer cell line caused decreases in the EMT-associated transcription factors Snail and Twist and decreases in phosphorylated Smad3." (PMID 27167191, 2016). "TMEPAI knockdown in another TGF-β resistant triple negative breast cancer cell line HCC1937 also resulted in increased Smad3 driven 12XCAGA signaling, reduced growth of cells with enhanced R-Smad phosphorylation in the presence or absence of TGF-β just like in MDA-MB-231 cells." (PMID 25352949, 2014). "Furthermore, C. phaeocaulis– and S. stoloniferum–medicated serum might suppress TGF-β1–induced EMT in triple-negative breast cancer by decreasing the phosphorylated Smad3 pathway in vitro." (PMID 34220510, 2021). "When functioning as a molecular mediator, in triple-negative breast cancer 41, DARS-AS1 overexpression significantly upregulated the levels of TGF-β, p-Smad3, ATG5, and the conversion from LC3-I to LC3-II." (PMID 38322590, 2024). "In turn, Pin1–Smad3 interaction is reduced by the inhibition of CDK-mediated Smad3 phosphorylation, leading to the suppression of triple negative breast cancer cells." (PMID 32296699, 2020). "Notably, YTHDC1 is vital for triple-negative breast cancer progression because it increases cancer cell survival and TGF-β-mediated EMT via SMAD3 to promote distant metastasis, highlighting the therapeutic potential of targeting the YTHDC1–m6A–SMAD3 axis." (PMID 40986143, 2025).
triple-negative breast carcinoma (continued). "For example, in triple-negative breast cancer, KAT6A promotes interactions between SMAD3 and TRIM24 by mediating SMAD3 acetylation and inhibiting interactions between SMAD3 and TRIM33, thereby promoting tumor progression by regulating the immune microenvironment." (PMID 36611207, 2023). "Furthermore, RBMS3 has been reported to stabilise several members of the SMAD family such as SMAD2 in zebrafish and SMAD2, SMAD3 and SMAD4 in triple-negative breast cancer cells." (PMID 36421707, 2022). "Similarly, in triple-negative breast cancer (TNBC), PCK2 modulates Smad3 expression and phosphorylation by inhibiting TRIM67-mediated Smad3 ubiquitination; this action consequently enhances TGF-β-stimulated Smad3 activity and activates TGF-β/Smad3 signalling." (PMID 40969268, 2025). "Taken together, our data demonstrate a novel role for Smad3 in cancer transformation and cancer progression through TMEPAI and further suggest that selective targeting of TGF-β-Smad3-TMEPAI axis may be beneficial in triple negative breast cancer therapy and prevention." (PMID 31798766, 2019). "Activation of CDK2 in triple negative breast cancer (TNBC) can contribute to non-canonical phosphorylation of a TGFβ signaling component, Smad3, promoting cell proliferation and migration." (PMID 29137393, 2017).
Marfan syndrome (19 papers, 2014 to 2025). A disorder of the connective tissue. "Potential phenotypes resulting from SMAD3 variants can range from minimal features to those observed in Marfan syndrome, Loeyz–Dietz syndrome type III (LSD3) or even vascular Ehlers–Danlos syndrome." (PMID 32597575, 2020). "In the aortic tissue of patients with familial ATAA, Marfan syndrome, or patients who have mutations in TGFB2, TGFB3, TGFBR or SMAD3, increased TGFB signaling was reported." (PMID 37238945, 2023). "Mutations of SMAD3 cause FTAAD in 2% of cases and are also causative of Marfan syndrome and Loeys–Dietz syndrome." (PMID 36830724, 2023). "We compared clinical manifestations and outcomes both between the Loeys-Dietz syndrome versus Marfan syndrome groups, and within the Loeys-Dietz syndrome group according to the pathogenic variant in the TGFBR1, TGFBR2, and SMAD3 gene." (PMID 31795342, 2019). "Mutations in MYLK cause a vascular disease that is different both from that in Marfan syndrome and from that associated with mutations that disrupt TGF-β signaling pathways (mutations in TGFβR1, TGFβR2, SMAD3, TGFβ2, TGFβ3)." (PMID 27586135, 2016). "Marfan syndrome (MFS) is associated with FBN1 mutations; Ehlers–Danlos syndrome (EDS) is relevant to the COL3A1 mutation; Loeysؘ–Dietz syndrome (LDS) is related to TGFBR1 or TGFBR2 mutations as well as SMAD3 or TGFB2 mutations." (PMID 36291545, 2022). "Well-known examples are Marfan syndrome (MFS) with a mutation in the extracellular matrix protein Fibrillin-1, Loeys-Dietz syndrome (LDS) with mutations in genes including the TGF-β-receptors 1 and 2, and SMAD3." (PMID 31683995, 2019). "Causative genes include autosomal polycystic kidney disease (PKD1, PKD2), Ehlers–Danlos syndrome (COL3A1), Marfan syndrome (FBN1), Loeys–Dietz syndrome (TGFB2, TGFB3, TGFBR1, TGFBR2, SMAD2, SMAD3), and Majewski Osteodysplastic Primordial Dwarfism (PCNT)." (PMID 40004483, 2025). "The best characterized genes include FBN1 [Marfan syndrome (MFS)], TGFBR1 and TGFBR2 [Loeys-Dietz syndrome (LDS)], SMAD3 [aneurysm-osteoarthritis syndrome (AOS)], and ACTA2 [Aortic and Cerebral Aneurysm (ACA)]." (PMID 36312254, 2022).